CCL2 (C-C motif chemokine ligand 2)
Diseases named in the same sentence as CCL2 in open-access papers (continued):
Sharing a sentence is not in itself a finding about the gene and the disease.
diabetes (continued). "The results of our research suggest that EGFR, CCL2, PTGS2 and SERPINE1 proteins that play a significant role in the diabetic cardiomyopathy network may function as a druggable node to impact the repercussions of diabetes in cardiomyocytes." (PMID 40282226, 2025). "Importantly, we showed elevated gene expression of PPARδ, CD36, and CCL2 in monocytic cells from OB individuals with diabetes compared with those without." (PMID 38989454, 2024). "Diabetes is a disease that triggers chronic hyper-inflammatory conditions, impairing the activity and presence of neutrophils, monocytes and dendritic cells that result in pro-inflammatory and chemotactic mediators’, such as IL-6, MCP-1 (CCL2), IL-1, TNF-α, IL-4 and IFN-γ, persistent secretion." (PMID 36078106, 2022). "CCL2, CCL8, and CXCL10 have also been demonstrated to play a role in the development of diabetes." (PMID 36299624, 2022). "Higher CCL2 concentrations were found in patients with post-transplantation diabetes mellitus, although no statistical significance (p = 0.08) was reached, which may have resulted from the small size of the study group." (PMID 34768469, 2021). "For example, circulating concentration of monocyte chemoattractant protein-1 (MCP-1/CCL2) has been shown to correlate with the degree of interstitial macrophage infiltration in human DKD while, experimentally, inhibition of MCP-1 in models of diabetes mellitus (DM) ameliorates renal injury." (PMID 31744554, 2019). "We asked whether the plasma levels of MCP-1/CCL-2, which is a signature inflammatory marker, were elevated in T2D patients with asthma as compared with those having either diabetes or asthma or none of the morbid condition." (PMID 27709105, 2015). "Similarly, renal gene expression of Il1β, Il18 and Ccl2 as well as glomerular accumulation of CD68-positive cells, which is a macrophage marker, were increased in the MCC950-treated diabetic animals, consistent with MCC950 promoting renal inflammation in diabetes." (PMID 35048962, 2022). "In the present study, patients with higher plasma CCL2 levels had a tendency to develop post-transplantation diabetes mellitus, although no statistical significance (p = 0.08) was shown in this case, which may have resulted from the small size of the study group." (PMID 34768469, 2021). "GCG, IRS1, VEGFA, STAT3, CCL2, CASP3, and APOE are the 7 DEPs that are related to diabetes mellitus as specific proteins but not seen among the central proteins of fatty liver disease." (PMID 35154608, 2021). "In this study, benign prostate tissues of patients with T2D showed elevated expressions of CCL2 and CCL5 than samples of patients without diabetes." (PMID 33207809, 2020). "After adjusting sex, age, BMI, smoking, drinking, history of CHD, hypertension, and diabetes or HDL-C, apoA1, TC, TG, and LDL-C, CCL2 was still negatively correlated with HDL2." (PMID 27458015, 2016).
Sepsis (305 papers, 2006 to 2026). Sepsis is defined as life-threatening organ dysfunction caused by a dysregulated host response to infection. "Previous evidence implicated CCL2 as critical for orchestrating macrophage recruitment and bacterial clearance in sepsis." (PMID 40892465, 2025). "MCP-1/CCL2 has a protective effect in murine endotoxemia, and administration of blocking monoclonal antibodies or genetic deficiency of MCP-1/CCL2 is associated with increased mortality rates in mice with sepsis." (PMID 24069320, 2013). "Upregulation of C-C motif chemokine ligand 2 (CCL2) causes renal dysfunction during sepsis." (PMID 40426888, 2025). "Therefore, we used in vitro and in vivo models to clarify how LDO mitigates sepsis and the associated pulmonary injury through a CCL2-dependent pathway." (PMID 40171016, 2025). "Hyperferritinemia and MCP-1/CCL2 were also causally associated with reduced ex vivo whole blood TNF response to endotoxin implying that targeting hyperferritinemic sepsis and macrophage activation could also improve infection clearance." (PMID 37674218, 2023). "Indeed, MCP-1/CCL2 has been implicated in sepsis triggered LD formation, whereas IL-10 and CCL3 were shown to participate in mechanisms of mycobacterial LD formation." (PMID 29875768, 2018). "In addition, propofol also protected the kidney from sepsis-induced injury, and the underlying mechanism was mediated, at least partially, by regulation of miR-290-5p/CCL-2 signaling pathway." (PMID 30328934, 2018). "Although CCL2 is primarily implicated in the recruitment of monocytes/macrophages to the inflammatory site, it is highly expressed in the monocytes from patients with sepsis, who show marked ET." (PMID 28824640, 2017). "Given that chemokine plasma levels, including of CXCL8 and CCL2 have been shown to be predictive of survival and correlate with sepsis severity, it is tempting to speculate that the loss of DARC expression may affect the outcome in sepsis." (PMID 22912641, 2012). "DHA treatment also reduced CD157 cell surface levels and CCL2 secretion, both contributors to tissue invasion and injury during sepsis." (PMID 41703318, 2026). "Mechanistically, by robustly attenuating STING signaling cascades and HK2-driven glycolysis, LDO actively down-regulates macrophage chemokine signaling pathways, especially CCL2, thus opening new avenues for targeted interventions in sepsis management." (PMID 40171016, 2025). "We monitored the time course of induction of the major mediators of inflammatory response to sepsis in blood by measuring the protein levels of 5 cytokines and 1 chemokine MCP1 (CCL2) in plasma." (PMID 41229427, 2025). "Elevated CCL2 levels in the serum of sepsis patients and animal models correlate closely with sepsis-related mortality." (PMID 40520010, 2025). "CCL2 supplementation or IGFBP6 deficiency effectively counteracts these pathological effects, aligning with prior sepsis studies." (PMID 40892465, 2025). "As expected, IL-4, IL-6, IL-10, IL-17, TNF-α, and CCL2 were significantly elevated from the early stage of sepsis, but on CLP day 6, all cytokines were reduced to levels similar to those of sham mice." (PMID 38385073, 2024). "Monocyte chemoattractant protein-1 (MCP-1) (CCL2) expression from LPS-stimulated endothelial cells certainly contributes to the pathophysiology of sepsis." (PMID 36975512, 2023). "miR-290-5p activated by propofol ameliorated a sepsis-induced mouse AKI model by targeting C-C motif chemokine ligand 2 (CCL2), thereby mediating an anti-apoptosis effect." (PMID 37761260, 2023). "CXCL-1 and CCL2 are chemokines crucial for the recruitment of neutrophils and monocytes during inflammation; and sepsis induces chemokine receptor expression on peripheral neutrophils." (PMID 35625756, 2022). "Since MCP-1/CCL2 shows a protective role in a similar mouse model (a polymicrobial sepsis model with LPS), DAG-deepVASE suggests a therapeutic potential to the detrimental interaction between IFN-γ and TNF-α." (PMID 37395630, 2022).
Sepsis (continued). "As expected, CLP sepsis in WT mice caused significantly increased expression of both CXCL-1 and CCL2 compared to sham control." (PMID 35625756, 2022). "SCH772984 treatment improved survival in the LPS-induced lethal endotoxemia and cecal ligation and puncture (CLP) mouse models of sepsis, and reduced plasma levels of Ccl2/Mcp1." (PMID 34638546, 2021). "For example, in a murine model of sepsis, amitriptyline decreased the serum levels of CCL2 and CXCL1 (KC, keratinocyte-derived chemokine)." (PMID 33945102, 2021). "Together, these results indicate that ERK1/2 blockage with a specific inhibitor improves the survival of animals in two models of sepsis and significantly dampens Ccl2 serum levels in a course of sepsis." (PMID 34638546, 2021). "The role of CCL2, a member of the chemokine CC subfamily with potent monocyte chemotactic activity, in sepsis is unclear." (PMID 32407417, 2020). "In our results, the cytokine profiles of the lung environment showed an increase of Ccl2 and Il4 transcripts, 10 days after sepsis." (PMID 32425929, 2020). "CCR2, the receptor for MCP-1 (CCL2) has also been found up-regulated in macrophages in lungs from patients with sepsis-induced lung injury." (PMID 32154187, 2020). "Chorioamnionitis and sepsis are risk factors for BPD development and amniotic fluid levels of CCL2 are higher in premature infants with intra-amniotic infection compared to the ones without infection." (PMID 30459472, 2018). "The plasma concentration of CCL-2 in sepsis patients is significantly higher than in healthy controls." (PMID 30328934, 2018). "We conclude that MCP-1/CCL2 plays a significant role in the pathogenesis of sepsis, which has potentially important therapeutic implications." (PMID 28472164, 2017). "Secretion of PGE2 and CCL2 has shown to be important to attenuate sepsis, local inflammation and mediates autoimmune disorders." (PMID 28595619, 2017). "This study provides valuable clinical evidence that the MCP-1/CCL2 polymorphisms rs1024611 and rs2857656 are associated with sepsis susceptibility and development." (PMID 28472164, 2017). "We also observed that compstatin treatment efficiently reduced the expression of sepsis-induced chemokines involved in fibrocyte recruitment into tissues, including CCL2 (MCP1) and CXCL12." (PMID 26337158, 2015). "Taken together, our data connect for the first time the sepsis-promoting functions of IFNs-I to the CCL2-mediated recruitment and the activation of inflammatory monocytes/DCs with high host-destructing potency." (PMID 22911155, 2012). "Several other products implicated in the pathogenesis of sepsis were also induced by this treatment, including IL-12p40, CCL5/RANTES, CXCL1/KC, CCL9/MIP-1γ, CXCL2/MIP-2, P-Selectin, TIMP-1 and CCL2/MCP-1." (PMID 19284588, 2009). "Notably, our analyses revealed dynamic CCL2 upregulation in PLF during early sepsis, which was substantially attenuated by rIGFBP6 administration, with minimal alterations observed in other cytokines/chemokines." (PMID 40892465, 2025). "(c) PHB2/STAT1/CCL2 axis modulation reverses IGFBP6-mediated sepsis pathology." (PMID 40892465, 2025). "However, they showed an impaired migration ability toward CCL2 compared to BM monocytes from naïve mice, which suggested that surviving monocytes in the BM after sepsis had lost their capacity to migrate out of the BM." (PMID 39040105, 2024). "Along with these changes, the mRNA levels of inflammatory mediators such as tumor necrosis factor-α (Tnf-α), chemokine ligand 2 (Ccl2), interleukin-6 (Il-6), interleukin-1β (Il-1β), and nitric oxide synthase 2 (Nos2) also demonstrated a marked elevation in the sepsis group." (PMID 38705396, 2024). "Study found that cytokines such as CCL2/MCP‐1, IL‐10, IL‐2, and TNF‐alpha were associated with lymphocyte morphology changes and other laboratory test results related to inflammation in sepsis, and those parameters were decreased in sepsis recovery." (PMID 39305165, 2024).
Sepsis (continued). "As sepsis is a systemic intravascular infectious disease, during sepsis, the endothelial cells in the cerebrovascular blood vessels also produce various chemokines, such as CCL2, CCL3, CCL5, CXCL1, CXCL2, CX3CL1, and CXCL8." (PMID 38585633, 2024). "Sepsis-induced neutrophil infiltration and lung damage was attenuated upon blocking CCL2." (PMID 35625756, 2022). "As we have known, the CCL2 plays significant role in sepsis and/or endotoxemia related organs’ injuries; however, there were few studies that compare the cellular CCL2 distribution in the brain GM and the WM of normal subjects and the subjects suffering from sepsis or endotoxemia." (PMID 35354428, 2022). "Propofol could serve as an effective therapeutic medication to suppress sepsis-induced renal injury in vivo and in vitro by regulating the miR-290-5p/CCL-2 signaling pathway." (PMID 30328934, 2018). "All of these findings suggest that propofol can serve as an effective therapeutic medication to suppress sepsis-induced renal injury in vivo and in vitro by activating miR-290-5p and the subsequent inhibiting CCL-2 and its downstream pathways, such as the inflammatory response." (PMID 30328934, 2018). "Based on our data, apyrase treatment might render monocytic cells non-responsive to the small, but substantially elevated, concentrations of plasma CCL2, as detected in sepsis, sarcoidosis, subclinical atherosclerosis and type II diabetes." (PMID 25271060, 2014). "Notably, higher levels of CCL2 and IL-6 in spleen are markers of lethal tularemia, suggesting that the utilization of glutamate might contribute to host sepsis and death." (PMID 40880474, 2025). "Similarly, the selective MCP-1/CCL2 inhibitor Bindarit is beneficial in experimental sepsis." (PMID 37674218, 2023). "Secretion of MCP-1 (CCL2) by BM stromal cells is part of physiological response to infection supporting mobilization of inflammatory monocytes but its local effect on HSPCs in sepsis remains unknown." (PMID 34367170, 2021). "In addition, the regulating effect of CCL-2 on inflammatory cytokines might exist in the progression of sepsis-associated AKI, but the effect of CCL-2 gain-of-function or loss-of-function on inflammatory response is still not elucidated." (PMID 30328934, 2018). "Our previous research demonstrated that the Tlr2/NF‐κB signalling axis upregulates CCL2 in proximal tubular epithelial cells, significantly promoting inflammation and AKI during sepsis." (PMID 40717237, 2025). "C-C chemokine ligand 2 (CCL2), C-X-C chemokine ligand 8 (CXCL8)/IL-8, and CXCL2 have been widely studied in sepsis-induced myocardial injury." (PMID 40520010, 2025). "In sepsis models, LDO effectively attenuates CCL2-driven cytokine storms, alleviates acute lung injury, and significantly enhances survival via metabolic reprogramming." (PMID 40171016, 2025). "In vivo, CCL2 counteracted the anti-inflammatory effects of LDO, worsened sepsis, and reduced survival." (PMID 40171016, 2025). "The results showed that the levels of Tnfα, IL-1β, CXCL2, CXCL10, CCL2, and CCL3 increased significantly in response to sepsis sEVs compared with healthy sEVs." (PMID 38910259, 2024). "The increased expression of CCL2 and CCL20 prevents pneumococcus-mediated sepsis in humans and mice (101, –, 103)." (PMID 36877045, 2023). "Interleukin (IL)-6 is a key inflammation regulator of sepsis in NEC, and the C–C Motif Chemokine Ligand 2 (CCL2) is induced from the bone marrow to migrate white blood cells." (PMID 37217485, 2023). "Our results showed that genes such as IFN-γ, TNF-α, IL-6, MIP-2, IL-10, KC (CXCL1), CCL-2, MPO, MMP9, TLR2, and LCN2 were significantly upregulated in the lungs of sepsis-induced ARDS mice compared to control mice." (PMID 37822934, 2023). "Among the downstream regulated genes, C–C motif chemokine 2 (Ccl2, also known as MCP‐1) has been found to be activated by NF‐κB in the context of inflammatory responses including SIRS and sepsis." (PMID 35548710, 2022).
Sepsis (continued). "IL-2R, IL-6, IL-8, IL-10, CCL-2, ICAM-1, and Urokinase were significantly higher in sepsis patients than SIRS patients." (PMID 35363162, 2022). "The elevated CCL2 and IL-12p70 observed in LOS infants is consistent with data on neonatal and adult sepsis." (PMID 32407417, 2020). "Reportedly, treatment with IL-34 also assisted to protect mice against polymicrobial sepsis by inducing the expression of cytokines (IL-6, TNFα) and chemokines (CXCL1, CCL2)." (PMID 32231137, 2020). "Several chemokines have been identified as biomarkers for sepsis, such as CXCL8, CXCL13, CCL2, and CCL8." (PMID 32500306, 2020). "For the chemokines, CCL2 and CCL3 levels were elevated in the middle sepsis phase (12 h), while CCL5, CXCL9, and CXCL10 levels were significantly increased in the late phase." (PMID 31354717, 2019). "We profiled cytokine interleukin-6 (IL6) in addition to chemokines interleukin-8 (IL8) and monocyte chemoattractant protein-1 (MCP-1/CCL2), which have been shown to be highly induced in many inflammatory diseases including sepsis." (PMID 28726766, 2017). "During the early hyperinflammatory phase of sepsis, plasma levels of proinflammatory cytokines TNF-α and IL-6, as well as the chemokine monocyte chemoattractant protein 1 (MCP-1/CCL2), are dramatically increased." (PMID 28628637, 2017). "γδ T lymphocytes present in the lungs of CLP mice were likely to be originated from peripheral lymphoid organs and migrated towards CCL2, CCL3 and CCL5, which were highly produced in response to CLP-induced sepsis." (PMID 26037291, 2015). "We concluded that administration of exogenous rPAF-AH reduced inflammatory injury, altered cytokine levels and favored bacterial clearance with a clear impact on mortality through modulation of MCP-1/CCL2 and NO levels in a clinically relevant sepsis model." (PMID 24069320, 2013). "Our study provides a novel mechanism for the role of IFNs-I in sepsis progression, coupling IFN-I target genes such as CCL2 and iNOS to the recruitment and activation of inflammatory monocytes/DCs with considerable host-destructive potential." (PMID 22911155, 2012). "Early sepsis disease 12 h post-infection was characterized by cytokine storm, with concentrations of IFN-γ, CCL2, IL-6, IL-17A, IL-1α, IL-10 and M-CSF significantly elevated in multiple tissues up to 7 days post-infection when mice had recovered from objective clinical measures of disease." (PMID 41910926, 2026). "Although the literature suggests a dual role for CCL2/MCP1 (proinflammatory and cardiac injury), we have focused on the chemotactic effect of CCL2 on macrophages, which is crucial for early bacterial clearance in sepsis." (PMID 40892465, 2025). "The identification of the tubular TLR2/NF-κB/CCL2 signaling pathway and the inhibition of the TLR4/NF-κB pathway represent promising strategies for addressing purulent AKI and related renal injuries in sepsis." (PMID 40386784, 2025). "Their study suggests that endogenous release of CCL2 within proximal renal tubules might contribute to renal inflammation and AKI induced by sepsis." (PMID 40386784, 2025). "This review links molecules (TNF-α, CCL2, ROS, VEGF, MMP-9, and NO) secreted by macrophages under inflammatory conditions to endothelial cell dysfunction (adhesion, permeability, and coagulability), refining the pathophysiologic mechanisms of sepsis." (PMID 39199368, 2024). "Of note, frTECs did not exhibit increased Ccl2, which was previously shown to be upregulated in the PTs of sepsis-induced AKI55." (PMID 38172172, 2024). "Ccl2 elevation has been reported in peripheral circulation of sepsis patients with gram‐negative infection." (PMID 35548710, 2022). "Elevated plasma concentrations of IL-10, IFN-γ, IP-10, IL-12p70, IL-6 and CCL2, were strongly associated with confirmed LOS compared to no LOS; consistent with other preterm infant sepsis studies." (PMID 32407417, 2020).